PCP4L1 (Purkinje cell protein 4 like 1)
Synonyms: IQM1
Tractability: No criterion of Open Targets' tractability assessment is met for any kind of drug.
Gene: Protein-coding gene on chromosome 1 (161,258,136 to 161,285,450, forward strand). Ensembl gene ENSG00000248485.
Subcellular location (Human Protein Atlas): Mitochondria; Nucleoplasm
Genetic constraint (gnomAD): Loss-of-function variants: 9 observed, 7.61 expected, observed/expected ratio (o/e) 1.18, 90% interval 0.7 to 1.84. That is too few expected variants to judge how well the gene tolerates losing a copy. Missense variants: 81 observed, 79.94 expected, observed/expected ratio (o/e) 1.01, 90% interval 0.85 to 1.22. Synonymous variants: 31 observed, 27.77 expected, observed/expected ratio (o/e) 1.12, 90% interval 0.84 to 1.51.
Homologues: Orthologues: chimpanzee PCP4L1 (100% identical), guinea pig PCP4L1 (94% identical), dog PCP4L1 (91% identical), pig PCP4L1 (90% identical), mouse Pcp4l1 (87% identical), rat Pcp4l1 (84% identical). Paralogues in human: PCP4 (40% identical).
Diseases named in the same sentence as PCP4L1 in open-access papers:
PCP4L1 is named in the same sentence as 10 diseases in open-access papers, as found by Europe PMC text mining. Sharing a sentence is not in itself a finding about the gene and the disease. The quoted sentences say what the papers report.
diabetes (3 papers, 2015 to 2021). "Genetics are heavily linked to the susceptibility of T2D and the comparison of the NZO and B6-ob/ob genomes lead to the identification of several diabetes genes like Lefty1, Apoa2, Pcp4l1 and others." (PMID 34445304, 2021). "Recently, PCP4L1 has been found to be involved in the development of diabetes and urinary bladder and colorectal cancer." (PMID 32873321, 2020). "In summary, our data indicate that Lefty1, Apoa2, Pcp4l1 and Ifi202b modify beta-cell proliferation, and suggest that the alteration of their expression contributes to the development of severe diabetes in the NZO mouse strain." (PMID 26348837, 2015). "A link of Pcp4l1 and diabetes has not been described so far." (PMID 26348837, 2015).
Anxiety (1 paper, 2013). Intense feelings of nervousness, tension, or panic often arise in response to interpersonal stresses. "The lower voluntary activity, the higher anxiety (O-maze), and reduced activity (water maze) of B6 allele carriers appear to be mediated by the microdeletion and/or variants in its close proximity that finally modulate expression of genes like Dusp23 and Pcp4l1 presumably in a cis-acting manner." (PMID 23308133, 2013).
lung adenocarcinoma (1 paper, 2024). A carcinoma that arises from the lung and is characterized by the presence of malignant glandular epithelial cells. "The low expression levels of down-regulated DEGs PLA2G3, PCP4L1, NINJ2, MIR186, and KLRG1 were also statistically correlated with a shorter OS in lung adenocarcinoma." (PMID 38183079, 2024).
prostate carcinoma (1 paper, 2022). A carcinoma that arises from epithelial cells of the prostate gland. "While C8orf37 has been only associated with genetic disorders, the possible involvement of PCP4L1 in CRC and prostate cancer progression requires further confirmation." (PMID 36497462, 2022).
infection (1 paper, 2015). The state of being infected such as from the introduction of a foreign agent such as serum, vaccine, antigenic substance or organism. "Infection of cells with the Lefty1, Pcp4l1, and Apoa2 encoding viruses increased BrdU incorporation by 87%, 80%, and 92%, respectively; overexpression of Ifi202b decreased the number of BrdU positive cells by 43%." (PMID 26348837, 2015).
tumours (1 paper, 2021). "In summary, the following marker genes were used for subsequent analysis in supratentorial tumours: RELA, ELL3, FBP2, PCP4L1, and MYO3A for detection of RELA+ tumours; and MRAP, IGF1, CAPS, and WWC1 for detection of YAP1+ tumours." (PMID 34314101, 2021).
PCP4L1 also shares sentences with these, for which no sentence is quoted: bladder (1 paper); colorectal cancer (1); genetic disorders (1); Obesity (1).